RASAL2 (RAS protein activator like 2)
Diseases named in the same sentence as RASAL2 in open-access papers (continued):
Sharing a sentence is not in itself a finding about the gene and the disease.
ovarian carcinoma (continued). "Finally, DAB2IP and RASAL2 mutations or deletions have been reported in different tumor types, including breast (both), gastrointestinal (DAB2IP), colorectal, lung, and ovarian cancer (RASAL2)." (PMID 33096593, 2020). "Furthermore, RASAL2 expression was negatively correlated with E-cadherin in primary human ovarian cancer." (PMID 25216515, 2014). "Because RASAL2 belongs to the RasGAP family, we investigated whether RASAL2 regulated the Ras-ERK pathway in ovarian cancer." (PMID 25216515, 2014). "To further investigate the significance of RASAL2 down-regulation in ovarian cancer, we determined whether RASAL2 suppression might also promote migration and invasion." (PMID 25216515, 2014). "Because down-regulation of RASAL2 occurs during ovarian cancer, restoring RASAL2 expression or synthesizing a small molecule that can replace RASAL2 and recover the hydrolysis of GTP by Ras may become a novel approach to cancer therapies." (PMID 25216515, 2014). "Collectively, these results indicate that RASAL2 is a potential tumor suppressor gene, and down-regulation of its expression may play a role in promoting the progression of ovarian cancer." (PMID 25216515, 2014). "The results showed that RASAL2 expression was significantly lower in tumor samples than in normal ovarian tissue samples, which are postulated to be the tissues of origin for the majority of ovarian carcinomas." (PMID 25216515, 2014). "In conclusion, we have identified RASAL2 as an EMT regulatory protein in ovarian cancer." (PMID 25216515, 2014). "In the present study, we explored RASAL2′s potential role in ovarian cancer." (PMID 25216515, 2014). "In addition, the depletion of RASAL2 promoted anchorage-independent growth of ovarian cancer cell lines (SK-OV-3, OVCAR3 and A2780) in vitro." (PMID 25216515, 2014). "We further investigated whether RASAL2 depletion promoted EMT of ovarian cancer cells in vivo." (PMID 25216515, 2014). "Finally, we examined whether RASAL2 expression correlated with E-cadherin expression in ovarian cancer patient samples." (PMID 25216515, 2014). "RAS protein activator-like 2 (RASAL2), a GTPase activating protein (GAP) that has been identified in ovarian cancer as a tumor suppressor, plays an important role in EMT and metastasis." (PMID 26356073, 2015). "In the current study, we found that the expression of RASAL2, a rarely reported GAP protein, was down-regulated during ovarian cancer." (PMID 25216515, 2014). "In this study, we identified RASAL2 as a regulator of epithelial-mesenchymal transition (EMT) and metastasis in ovarian cancer." (PMID 25216515, 2014). "Together, our results implicate RASAL2 as an EMT regulator and tumor suppressor in ovarian cancer, and down-regulation of RASAL2 promotes ovarian cancer progression." (PMID 25216515, 2014). "Nevertheless, RASAL2 was reported to regulate EMT process in lung and ovarian cancers previously." (PMID 30037330, 2018). "Our study shows that the expression of RASAL2 is negatively correlated to FIGO stages and pathological grading, which indicates that low expression of RASAL2 may relate to the progression of ovarian cancer." (PMID 25216515, 2014). "The reduction in the expression of RASAL2 paralleled the progression of FIGO stages and pathological grading, which indicates that low-expression of RASAL2 may relate to the progression of ovarian cancer." (PMID 25216515, 2014). "Therefore the PI3K-AKT pathway may also participate in EMT which was mediated by down-regulation of RASAL2, raising the possibility that the PI3K-AKT pathway inhibitors or mTOR pathway inhibitors, such as rapamycin, may also be effective in the treatment of Ras pathway-activated ovarian cancer." (PMID 25216515, 2014).
bladder cancer (7 papers, 2017 to 2022). "In bladder cancer, RASAL2 is downregulated and negatively associated with clinical stage." (PMID 31799194, 2019). "In our previous study, we reported that RASAL2 acted as a tumour suppressor in renal cancer and bladder cancer." (PMID 35668070, 2022). "RASAL2 functions as a tumor suppressor in a broad range of human tumors, including lung, ovarian, breast, and bladder cancer; low RASAL2 expression often correlates with aberrant Ras-ERK activation and worst prognosis." (PMID 33096593, 2020). "In our previous study, we reported that RASAL2 was downregulated in bladder and kidney cancers, which regulated angiogenesis, while RASAL2 also affected stemness and epithelial-mesenchymal transition in bladder cancer." (PMID 35668070, 2022). "Additionally, RASAL2 (RAS protein activator like 2) inhibited tumor angiogenesis via p-AKT/ETS1 (ETS proto-oncogene 1, transcription factor) signaling in bladder cancer." (PMID 33931059, 2021).
hepatocellular carcinoma (6 papers, 2018 to 2022). A malignant tumor that arises from hepatocytes. "A previous research revealed that upregulation of Rasal2 was able to phosphorylate AKT to promote proliferation in hepatocellular carcinoma." (PMID 35044284, 2022). "Additionally, PI3K/AKT signalling was found to be one of the common genomically altered pathways in mCRPC patients; in particular, a previous study suggested that RASAL2 promotes cancer cell proliferation through this pathway in hepatocellular carcinoma." (PMID 35668070, 2022). "However, in hepatocellular carcinoma, RASAL2 promoter was hypomethylated with an elevated expression of RASAL222." (PMID 30158581, 2018). "In hepatocellular carcinoma (HCC), RASAL2 is hypomethylated and RASAL2 is upregulated, thereby promoting invasiveness." (PMID 31799194, 2019).
renal cell carcinoma (6 papers, 2018 to 2022). "RASAL2 hypermethylation has been associated with higher stages and grades and worse survival rates in patients with renal cell carcinoma." (PMID 35308102, 2022). "Further, the epigenetic silencing of RASAL2 was negatively correlated with the overall survival of renal cell carcinoma patients." (PMID 31627186, 2019). "Additionally, Rasal2 is also reported to negatively modulate angiogenesis in renal cell carcinoma, suggesting the potential role of Rasal2 in regulating vascular pathological and physiological functions." (PMID 35044284, 2022). "In renal cell carcinoma (RCC), RASAL2 is usually epigenetically silenced and its loss is negatively associated with overall survival of RCC patients." (PMID 31799194, 2019).
pancreatic cancer (5 papers, 2018 to 2022). "Also, RASAL2 copy number gain was found in other gastrointestinal cancers, such as gastric, liver and pancreas cancer, in TCGA." (PMID 30037330, 2018). "Therefore, RASAL2 could be a potential novel biomarker of diagnosis and prognosis and target for pancreatic cancer treatment." (PMID 35844783, 2022). "In pancreatic cancer, one study done on different cell lines showed that SFN induced miR-135b-5p expression which, in turn, binds to the 3′UTR region of the Rat sarcoma (RAS) Protein Activator Like 2 (RASAL2) gene, leading to its up-regulation, having an anti-proliferative effect in vitro." (PMID 34295245, 2021).
nasopharyngeal carcinoma (4 papers, 2017 to 2022). A carcinoma arising from the nasopharyngeal epithelium. "RASAL2 also inhibited the metastasis capability and proliferation of nasopharyngeal carcinoma." (PMID 31799194, 2019).
breast tumor (3 papers, 2014 to 2021). "In human RASAL2 loss was associated with metastatic disease and decreased expression of RASAL2 was associated with the recurrence of luminal B breast tumors." (PMID 25051360, 2014). "For instance, RASAL2 expression is frequently suppressed in luminal B breast tumor cell lines and in primary tumors." (PMID 34966481, 2021).
liver cancer (3 papers, 2019 to 2022). An epithelial or non-epithelial malignant neoplasm that arises from the liver. "Interestingly, a controversial role for RASAL2 has emerged in colorectal cancer, lung cancer and liver cancer." (PMID 35668070, 2022). "And the role of RASAL2 in colorectal, lung and liver cancers has also emerged as controversial." (PMID 35668070, 2022).
lung adenocarcinoma (3 papers, 2019 to 2022). A carcinoma that arises from the lung and is characterized by the presence of malignant glandular epithelial cells. "Our evidence suggests that RASAL2 is a contributing factor to poor prognosis in lung adenocarcinoma." (PMID 34430085, 2021). "A novel four-gene signature (INPP5B, FOSL2, CDCA3, RASAL2) was established to predict relapse-related survival outcomes in patients with early lung adenocarcinoma after surgery." (PMID 34430085, 2021). "For example, in lung adenocarcinoma, downregulation of RASAL2 promotes migration capability due to EMT via ERK regulation." (PMID 31799194, 2019). "Thus, RASAL2 may be important in lung adenocarcinoma treatment." (PMID 31799194, 2019).
gastric cancer (2 papers, 2021 to 2025). A primary or metastatic malignant neoplasm involving the stomach. "In gastric cancer, RASAL2 has been found to be physically associated with protein phosphatase PP2A, leading to oncogenic activation of the β catenin signalling." (PMID 39890967, 2025). "In gastric cancer, RASAL2 binds to protein phosphatase 2 A, leading to oncogenic activation of β catenin signalling." (PMID 39890967, 2025). "We found that SHCBP1 and RASAL2 were really upregulated in HER2-positive gastric cancer." (PMID 33990570, 2021). "We screened out five overlapping Shc1-binding proteins (JUP, EPHA2, RASAL2, LYN, and SHCBP1), which were positively correlated with HER2 expression and were upregulated in gastric cancer." (PMID 33990570, 2021).
metastatic disease (2 papers, 2014 to 2018). "RASAL2 was overexpressed in primary and metastatic tumor samples in both array-CGH and expression microarray analyses." (PMID 30037330, 2018). "Out of 15 cases with both primary and metastatic tumor samples, 12 (80%) had a higher RASAL2 mRNA expression level in metastatic tumors than in their primary counterparts (P < 0.05)." (PMID 30037330, 2018). "When comparing the RASAL2 mRNA expression levels among normal colon mucosa, primary tumors and metastatic tumors, we found that metastatic tumors showed the highest RASAL2 expression, followed by primary tumors, and then normal colon mucosa." (PMID 30037330, 2018).
pancreatic ductal adenocarcinoma (2 papers, 2019 to 2022). An infiltrating adenocarcinoma that arises from the epithelial cells of the pancreas. "MiR135b-5p is induced by sulforaphane and then promotes the expression of RASAL2 to suppress pancreatic ductal adenocarcinoma." (PMID 31799194, 2019).
prostate carcinoma (2 papers, 2021 to 2022). A carcinoma that arises from epithelial cells of the prostate gland. "In this study, for the first time, we demonstrated that RASAL2 was upregulated in prostate cancer and associated with the cell cycle, tumour growth and poor disease prognosis, in which the PI3K/AKT signalling pathway and cyclin D1 expression played an important role." (PMID 35668070, 2022). "In summary, we have revealed the expression and role of RASAL2 in prostate cancer for the first time." (PMID 35668070, 2022). "Taken together, these findings indicate that RASAL2 plays an oncogenic role in prostate cancer and may promote PCa tumorigenesis through PI3K/AKT signalling and cyclin D1 expression." (PMID 35668070, 2022). "Additionally, Ingenuity Pathway Analysis suggested a crosstalk between RASAL2 and tumor necrosis factor alpha (TNFα) in prostate cancer." (PMID 34966481, 2021). "Thus, RASAL2 expression could potentially limit the function of RAS in prostate cancer (PCa)." (PMID 34966481, 2021).
astrocytoma (1 paper, 2019). "In astrocytoma cells, RASAL2 interacts with epithelial cell transforming factor 2 (ECT2), which activates Rho GTPases, in order to reduce Rho activity." (PMID 31799194, 2019).
colorectal tumors (1 paper, 2018). "We evaluated RASAL2 protein expression in primary and metastatic colorectal tumors as well as normal tissues by IHC on tissue microarrays." (PMID 30037330, 2018).
gastric tumor (1 paper, 2023). "A recent study demonstrated that the Hp infection could activate NF‐κB signaling pathway and upregulate RAS protein activator like 2 (RASAL2) expression to promote proliferation of gastric tumor cells." (PMID 37215622, 2023).
Lymphatic Metastasis (1 paper, 2018). Transfer of a neoplasm from its primary site to lymph nodes or to distant parts of the body by way of the lymphatic system. "Overexpression of RASAL2 was positively associated with advanced TNM stages (P = 0.018), including lymphatic metastasis (P = 0.013) and distant metastasis (P = 0.007)." (PMID 30037330, 2018).
lymphoma (1 paper, 2016). A malignant (clonal) proliferation of B- lymphocytes or T- lymphocytes which involves the lymph nodes, bone marrow and/or extranodal sites. "Mutational profiling of 26 coding loci in MSI+ GIT and lymphomas revealed instability in half of the microsatellites, two of them (Rfc3 and Rasal2) shared between both entities." (PMID 27447752, 2016).
melanoma (1 paper, 2016). A malignant, usually aggressive tumor composed of atypical, neoplastic melanocytes. "Tumor suppressive function of NF1 (neurofibromatosis type 1) in several cancer types including melanoma, DAB2IP in prostate cancer, RASAL2 in breast cancer, PLXNC1 (Plexin C1) and RASA2 in melanoma have been described." (PMID 26993606, 2016).
pulmonary hypertension (1 paper, 2022). Increased pressure within the pulmonary circulation due to lung or heart disorder. "In our current study, we observed elevated level of Rasal2 in both PA of chronic hypoxia-induced pulmonary hypertension (CH-PH) mice and PASMC after hypoxia stimulus." (PMID 35044284, 2022). "We found that the protein level of Rasal2 was increased in both pulmonary arteries of chronic hypoxia-induced pulmonary hypertension (CH-PH) mice and hypoxia-challenged PASMC." (PMID 35044284, 2022).
sarcoma (1 paper, 2024). A usually aggressive malignant neoplasm of the soft tissue or bone. "Interestingly, cytoskeleton proteins, including RASA1, RASAL2, NCKAP5, MACF1 and ARHGAP24, were reduced following differentiation, indicating that the sarcoma microenvironment induces resident‐like myeloid cell transfer." (PMID 39658531, 2024).
serous ovarian cancer (1 paper, 2019). "Similarly, RASAL2 is functionally equivalent with RASAL1 upregulation and gene copy number gain which is also found in high-grade serous ovarian cancer, and has recently been found to share a similar molecular portrait to TNBC through large-scale genomic analyses." (PMID 33817145, 2019).
tumor (33 papers, 2014 to 2025). "Overexpression of RASAL2 was associated with higher PCa tumor stage, Gleason score, and poorer prognosis." (PMID 40361412, 2025). "We also found that overexpression of RASAL2 was significantly associated with advanced tumor stages (III/IV) as well as lymphatic and distant metastases of CRC patients." (PMID 30037330, 2018). "Inactivation of RASAL2 was shown to be associated with tumor growth, progression and metastasis in animal models." (PMID 25051360, 2014). "Analyses of xenograft tumor sections revealed a loss of the epithelial nature of the tumor following RASAL2 knockdown in SK-OV-3 cells as evidenced by decreased E-cadherin expression." (PMID 25216515, 2014). "The RasGAP2 gene (RASAL2) is one such gene, it is a tumor and metastasis suppressor which is mutated or suppressed in breast cancer." (PMID 25051360, 2014). "Similarly, in breast cancer, mutations in RASAL2 have been reported to promote tumor growth, progression, and metastasis in mouse models." (PMID 40361412, 2025). "Moreover, high RASAL2 expression in these cells was strongly associated with a tumour transcriptomic signature derived from genes enriched in residual viable tumour population of patients treated with pre-operative chemotherapy." (PMID 39890967, 2025). "In contrast, RASAL2 is upregulated in triple-negative breast cancer and oestrogen-receptor negative breast cancer and is associated with poor prognosis, early metastasis, and tumour recurrence." (PMID 35668070, 2022). "We found that RASAL2 is a tumour-specific factor in residual TNBC and is capable of driving resistance towards a broad range of common chemotherapeutic agents beyond platinum." (PMID 39890967, 2025). "Accordingly, mitochondrial outer membrane permeabilisation assay using live mitochondria from RASAL2-high/chemoresistant tumour cells demonstrated attenuated release of death signal, cytochrome c, when exposed to pro-apoptotic factors BAX and tBID." (PMID 39890967, 2025). "In The Cancer Genome Atlas (TCGA) clinical cohort, TNBC tumours with high RASAL2 expression exhibited attenuated apoptotic signalling compared to those with low RASAL2 expression." (PMID 39890967, 2025). "Consistent with its role in driving chemoresistance, in patients, RASAL2 is enriched in residual tumours following neoadjuvant chemotherapy." (PMID 39890967, 2025). "For example, ablation of RASAL2 leads to tumour proliferation and metastasis in hormone receptor-positive breast tumours, as a result of RAS hyperactivation." (PMID 39890967, 2025). "This enrichment is specific to the tumour compartment compared to adjacent normal tissues, suggesting that RASAL2 upregulation is tumour-selective." (PMID 39890967, 2025). "In independent clinical cohorts, where RASAL2 was elevated in TNBC tumours post-treatment, BCL2 was also significantly elevated post-treatment." (PMID 39890967, 2025). "Through downregulation of RASAL2, miR-136 effectively inhibits tumor growth and metastasis, underscoring its therapeutic potential in TNBC." (PMID 40104500, 2025). "Collectively, these findings suggest that RASAL2 is a tumour cell-specific factor that is upregulated in residual treatment-resistant TNBC." (PMID 39890967, 2025). "SFN induces overexpression of novel tumor suppressors miR-135b-5p and RASAL2 in highly aggressive pancreatic cancer cell lines and effectively inhibits tumor cell growth in vitro and in vivo." (PMID 38902597, 2024). "To clarify the expression characteristics of RASAL2 in PCa, we performed immunohistochemistry on 19 matched groups of PCa tumour and metastatic lymph node tissues compared to their adjacent nontumor tissues." (PMID 35668070, 2022). "Through functional studies conducted in vitro and in vivo, we demonstrated that RASAL2 promoted cell proliferation and tumour growth in PCa." (PMID 35668070, 2022). "Ki67 staining was increased in xenograft tumor tissues of MIA PaCa-2 overexpressing RASAL2 and E-cadherin staining was decreased." (PMID 35844783, 2022).